CDKN1B (cyclin dependent kinase inhibitor 1B)
Diseases named in the same sentence as CDKN1B in open-access papers (continued):
Sharing a sentence is not in itself a finding about the gene and the disease.
cancer (continued). "CDKN1B haploinsufficiency promotes the development of several human cancers." (PMID 33316141, 2021). "Importantly, the increased cancer cell proliferation was accompanied with suppressed expression of the cyclin-dependent kinase inhibitor CDKN1B." (PMID 33598459, 2021). "The three clusters generated contained genes or proteins involved in apoptosis (BIRC3, BIRC5, PARP1, CASP8, and CASP9), transcriptional dysregulation in cancer (CDKN1B, RELA, CDKN1A, MYC, JUN, and MMP9), and cancer progression (CCND1, CASP3, CTNNB1, WNT1, and VEGFA) pathways." (PMID 34836311, 2021). "Several studies showed that CDKN1B obstructs anchorage-independent cell growth in cancer." (PMID 33435156, 2021). "Moreover, the proapoptotic effect of suppressed PFKFB3 activity can be explained by increased expression of cyclin-dependent kinase inhibitor 1B (p27) in cancer cells following PFKFB3 inhibition." (PMID 33922320, 2021). "Such discrepancy could be due to the use of different cell types and also implies the possibility that CDKN1B regulates anchorage-independent growth in cancer cells that already acquire anoikis resistance mediated by other factors." (PMID 33435156, 2021). "Reduced CDKN1B expression has been found to be a significant prognostic factor in other cancers." (PMID 33598459, 2021). "CDKN1B plays a vital role in the development, drug resistance, treatment, and prognosis of cancer." (PMID 32590883, 2020). "However, p27-depleted or CDKN1B-knockout cells generally proliferate better than control cells, CDKN1B-knockout mice are characterised by increased growth and tumourigenesis, and levels of p27 are often reduced in cancer." (PMID 33166394, 2020). "Cdkn1b is not frequently mutated in treatment-naïve human cancers and its homozygous deletion in mice did not lead to malignant growth." (PMID 30893315, 2019). "Deregulation of this miRNA is important for GC progression because it promotes cell proliferation by down-regulating the expression of CDKN1B (p27kip1) tumor suppressor and invasion and epithelial to mesenchymal transition of cancer stem cells by down-regulating the expression of SMAD4 in GC." (PMID 31275362, 2019). "CDKN1B was also a target gene of miR‐222‐3p in several cancers 13, 14, but the regulation by miR‐222‐3p of CDKN1B in NP cells remains unknown." (PMID 30984546, 2019). "Knockdown of Gls1 increased the expression of Cdkn1a and Cdkn1b and decreased the expression of some critical oncogenes for cancer cell survival, such as c-Myc, Cdk4, and NfκB, as well as some genes which are essential for MM cell survival, such as Irf4, Prdm1, Csnk1α1, and Rassf5." (PMID 31666930, 2019). "Finally, the LKB1/AMPK pathway activated by nutrient deprivation increases cyclin-dependent kinase inhibitor 1B (p27), which enhances autophagy and apoptosis processes in cancer cells." (PMID 30186236, 2018). "CDH1, FH, and CDKN1B are all involved in pathways in cancer." (PMID 29738475, 2018). "It is worth noting that mutations in any of these three genes may affect their predictive utility in this context, however this rarely occurs in HER2+ cancers (less than 10% harbor mutations in EGFR, ERBB3, or CDKN1B)." (PMID 27035903, 2016). "Moreover, it is involved in tumorigenesis through the activation of PLK1, BUB1B and C-MYC, and repression of CDKN1B during cancer progression." (PMID 27270442, 2016). "Beyond the cell cycle regulator CDKN1B (12p13.1), further potentially relevant cancer genes on 12p may for example include CD9, ING4, and BCL-G." (PMID 26293672, 2015). "The loss of CDKN2A, CDKN1B, and CDKN1A is a predictor of poor prognosis in several types of cancer." (PMID 24605326, 2014). "Reduced IRES-mediated translation, due to mutations in the pseudouridine synthase that alters the ribosome's ability to efficiently engage the CDKN1B IRES element, may contribute to the increased predisposition to cancer in X-linked congenital dyskeratosis." (PMID 23555276, 2013).
cancer (continued). "A possible explanation for its oncomiR function in this setting might derive from non-cancer models such as ARDS, where miR-877-5p suppressed CDKN1B which encodes p27Kip1, whose downregulation is claimed as one of the possible mechanisms of resistance to CDK4/6i." (PMID 38338777, 2024). "Furthermore, the presence of CDKN1B in a variety of patient cancer tissues was validated." (PMID 37432583, 2023). "It is still unknown whether CDKN1B has a role in the development of a number of cancers." (PMID 37432583, 2023). "In many cancer cell types, 1,25-(OH)2D3 directly arrests the cell cycle in the G0/G1 phase by downregulating cyclin-dependent kinases (CDKs: CDK4, CDK6) and repressing the genes that encode cyclins D1 and C (CCND1, CCNC) and CDK inhibitors p21CIP1/WAF1 (CDKN1A), p27KIP1 (CDKN1B) and p19 (CDKN2D)." (PMID 35406059, 2022). "The P27 (cyclin‐dependent kinase inhibitor 1B) inhibits cyclin/cyclin‐dependent kinase (CDK) complexes and halts cell cycle progression and regulates invasion and migration of cancer cells, functioning as either an oncoprotein or a tumor suppressor." (PMID 37042179, 2023). "Except for CDKN1B and RELA, the expression levels of CASP7, CDH3, EIF4G1, and EIF4EBP1 were increased significantly in most individual cancer stages compared with normal samples." (PMID 35787690, 2022). "CAFs are resistant to cisplatin and deliver exosomal miR-196a, which binds to target CDKN1B and ING5, mediates the expressions of p27, CDK2, CDK4, Cyclin D1 and Cyclin E1 and thus induces cisplatin resistance to cancer cells." (PMID 32299469, 2020). "Together, these results support our initial finding that that EGFR, ERBB3 and CDKN1B expression predict differential dependence on PI3K/AKT and MAPK signaling in HER2+ cancer cells." (PMID 27035903, 2016). "miR-24 directly targets CDKN1B and CDKN2A in keratinocytes and in different cancer-cell lines promoting their proliferation." (PMID 24605326, 2014). "Recent studies have reported that miR-221 and miR-222 regulate cell growth and cell cycle progression by targeting cyclin-dependent kinase inhibitor 1B (CDKN1B) and cyclin-dependent kinase inhibitor 1C (CDKN1C) in several cancer cell lines." (PMID 23563786, 2013). "• Exertion of anticancer effects through 3 major pathways: apoptosis (BIRC3, BIRC5, caspase-8, caspase-9, and PARP1), transcriptional dysregulation in cancer (CDKN1A, CDKN1B, MMP9, MYC, JUN, and RELA), and cancer progression (caspase-3, CCND1, CTNNB1, VEGFA, and Wnt-1)." (PMID 39181121, 2025). "Here, CDKN1B, PIAS4, CTBP2, and ABCC1 could be the potential source for ZNF143 to alter the major cancer signaling pathways." (PMID 36675976, 2022). "Based on this result, we could conclude that CDKN1B, PIAS4, CTBP2, and ABCC1 could be the potential source for ZNF143 (because these genes link more biological functions) to alter the major cancer signaling pathways." (PMID 36675976, 2022). "Furthermore, 11 KEGG pathways were also enriched, such as hsa05200:Pathways in cancer (CDKN1B, SMAD4), hsa04350:TGF-β signaling pathway (SMAD4) and hsa04110:Cell cycle (CDKN1B, SMAD4)." (PMID 31763681, 2020). "In HCT-15 cells, reduced transcription of cell cycle mediating genes (CCND1, PCNA, CDK2, CDKN1B), and reduced transcription of anti-apoptotic genes (BMI1, BIRC5 and BCL2), support a cancer suppressive and favorable FOXO3/FOXM1 ratio upon combined TNKSi/MEKi treatment." (PMID 30717152, 2019). "Overexpression of SKP2 which leads to reduced expression of negative cell cycle regulator CDKN1B is found in cancer cells as a bypass mechanism to escape cell cycle control." (PMID 28466007, 2017).
cancer (continued). "First, we sought to determine whether protein expression of EGFR, ERBB3 and CDKN1B, could be used to predict differential sensitivity to anti-cancer drugs in HER2+ cancers." (PMID 27035903, 2016). "Treatment of the human SW480 cancer cells with Echinacoside resulted in marked apoptosis and cell cycle arrest, together with a significant increase in active caspase 3 and cleaved PARP, and upregulation of the G1/S-CDK blocker CDKN1B (p21)." (PMID 26132569, 2015). "The loss of several tumor suppressor proteins by nonstop mutations, as verified for B2M, CDKN1B (p27KIP1) and MLH1 in this study, could have a relevant functional impact in cancer development and therapy." (PMID 39448564, 2024). "Using qPCR assay for known genes modulated NT157 in other cancer models, we identified that NT157 decreased expression of oncogenes BCL2, CCND1, MYB, and MYC and increased genes related to cellular stress and apoptosis, JUN, BBC3, CDKN1A, CDKN1B, FOS, and EGR1 (all p < 0.05)." (PMID 36224313, 2022). "Altogether, from the review of existing literature it is clear that many new insights, previously not hypothesized, on CDKN1B role and implications in cancer have been disclosed by the recent advent of next generation sequencing technologies." (PMID 30065701, 2018). "Notably, an increased reliance on CDK2 may be a therapeutic vulnerability, suggesting an opportunity for CDK2 inhibitors in cancers that delete CDKN1B (although, unlike CDK4/6 inhibitors, CDK2 inhibitors have not yet been successful in the clinic due to high toxicity)." (PMID 33166394, 2020). "However, in some other cancer cell types, in which FOXO1 does not regulate MDM2 transcription but instead activates CDKN1B transcription, FOXO1 may paradoxically act in a cancer-suppressing manner." (PMID 38519029, 2024). "Consequently, the G1/S-CDK suppresser CDKN1B (p21) and pro-apoptotic proteins Bax and activated caspase-3 were upregulated, while anti-apoptotic Bcl-2 was downregulated, which were followed by cell cycle arrest at G1 and marked apoptosis in ATL-treated cancer but not non-cancer cells." (PMID 27089328, 2016).
infection (15 papers, 2008 to 2025). The state of being infected such as from the introduction of a foreign agent such as serum, vaccine, antigenic substance or organism. "Infection of human neural stem cells with ZIKV was noted to elevate the expression of CDKN1B, a condition that might lead to hearing loss through overproduction of hair cells and supporting cells." (PMID 33419104, 2021). "However, in response to infection, male mice exhibited higher expression levels of CDKN1B, and CTNNB1 (KO, 1A3), TCF4 (1A0, 6A2), TAP1, and TAP2, (1A0), CDKN1A, (1A3, 6A2), MARCO, and MMP12 (1A3), CCND1, CDK2, IRF and MYC (6A2) compared to females." (PMID 32670284, 2020). "In our study, the expression of cyclin-dependent kinase inhibitor 1B (CDN1B), cyclin-dependent kinase 6 (CDK6) and cyclin-dependent kinase 1 isoform 1 (CDK1) was found to be downregulated during aMPV/C infection in Vero cells." (PMID 32231136, 2020). "Infection of lung and foreskin fibroblast cells with CMV contributes to the degradation of CDKN1B." (PMID 33419104, 2021).
adenocarcinoma (3 papers, 2010 to 2012). A common cancer characterized by the presence of malignant glandular cells. "The highest Cohen’s κ coefficient for discrimination between small cell, squamous cell and adenocarcinoma was found for CDKN1B, CSF and EGFR1 (κ = 0.177, p = 0.0041)." (PMID 22848476, 2012).
hematologic disorder (3 papers, 2015 to 2025). A disease involving the hematopoietic system. "ETV6 and CDKN1B, linked to cell cycle regulation and hematologic disorders, may also contribute to additional systemic manifestations." (PMID 40243517, 2025). "As the patient had an aberrant T-cell population, and some pathogenic CDKN1B variants have been associated with hematologic malignancy, the identified variant could represent either a germline or somatic variant." (PMID 36334246, 2023). "Genetic alterations of PTEN or CDKN1B (p27KIP1) are common in hematological malignancies." (PMID 27366593, 2015).
genetic disorder (1 paper, 2023). "The most common confirmed genetic disorder in our sample was FHH type 1 (due to CASR variants), followed by MEN4 (due to CDKN1B variants)." (PMID 37810884, 2023).
CDKN1B also shares sentences with these, for which no sentence is quoted: multiple endocrine neoplasia type 1 (14 papers); papillary thyroid carcinoma (10); acute lymphoblastic leukemia (8); diabetic nephropathy (8); lung adenocarcinoma (8); Carney complex (7); familial isolated pituitary adenoma (7); familial hypocalciuric hypercalcemia (6); Hyperglycemia (6); Hyperparathyroidism-jaw tumor syndrome (6); oral squamous cell carcinoma (6); gastric tumor (5); Hypercalcemia (5); malignant glioma (5); meningioma (5); sarcoma (5); multiple endocrine neoplasia type 2 (4); oral cancer (4); small cell lung carcinoma (4); Alzheimer disease (3); B-cell lymphomas (3); breast (3); diffuse large B-cell lymphoma (3); endocrine neoplasms (3); endocrinopathy (3); esophageal adenocarcinoma (3); head and neck squamous cell carcinoma (3); medulloblastoma (3); neurofibromatosis type 1 (3); pancreatic adenocarcinoma (3).
A further 169 diseases each share a sentence with CDKN1B in 3 papers or fewer.